CD4 (CD4 molecule)
Diseases named in the same sentence as CD4 in open-access papers (continued):
Sharing a sentence is not in itself a finding about the gene and the disease.
lupus (continued). "Although these double negative T cells might be secondary events in lupus compared to the CD4+ Th cells, they make an important contribution to pathogenesis of the disease." (PMID 33936042, 2021). "Proinflammatory immune cells, including B cells, plasma cells, CD4+ T cells, Tfh cells, GCB cells, IL-17a+ T cells, and IFN-γ+ T cells, were increased in sodium chloride-pretreated BMDC-ALD-DNA-induced lupus mice compared to those in control BMDC-ALD-DNA-induced lupus mice." (PMID 32296043, 2020). "To investigate such possibility, we performed analysis based on EWAS28 and EWAS29, two datasets from EWAS of systemic lupus erythematosus (SLE) using CD19+ B cells and CD4+ T cells, respectively." (PMID 32252795, 2020). "However, Yang and colleagues reported that the phenotype and functional activity of Tregs were scarce on CD4 + CD25-Foxp3 + in lupus patients, that not all CD4 + Foxp3 + T cells have protective suppressive function." (PMID 33013906, 2020). "Mature double negative (DN) T cells are a population of αβ T cells that lack CD4 and CD8 coreceptors and contribute to systemic lupus erythematosus (SLE)." (PMID 32503973, 2020). "In systemic lupus erythematosus (SLE), RFX1 downregulated IL17A, CD70, and CD11a expression by recruiting DNMT1, HDAC1, and SUV39H1 to alter epigenetic modifications in CD4+ T cells from patients with lupus." (PMID 30857550, 2019). "Mice receiving the treated, but not untreated Tcells developed lupus-like autoimmunity.Further, similar epigenetically altered CD4+ T cells were found in lupuspatients, and the number of the epigenetically altered cells was directly proportionalto flare severity." (PMID 31737868, 2019). "For example in systemic lupus erythematosus (SLE), the increased level of IFN-I produced by pDCs directly induced cDCs maturation and CD4+ T cell activation." (PMID 30416504, 2018). "Moreover, hyper Th17 response (with increased IL-17/IL-21 producing CD4+ T cells) is not observed in all of the lupus-prone mice." (PMID 30013031, 2018). "Given that pro-inflammatory cytokines are crucial in lupus pathogenesis, we also measured the cytokine production level in vitro that WT or B7-H4-KO BMDCs incubated with ALD-DNA and then co-cultured with wild-type normal CD4+ cells supernatants used a cytokine test kit named CBA (BD)." (PMID 29321778, 2017). "Interestingly, a unique CD4+ subset expressing DR6 was observed in autoreactive Ab positive lupus-prone BWF1 (aged 24 weeks) but not in autoreactive Ab negative B6 mice (aged 10 and 24 weeks)." (PMID 28045014, 2017). "Importantly, in homozygous CD19cre mice, thymic B cells mainly regulated thymic CD4-CD8+ but not CD4+CD8- T cells in lupus-induced mice." (PMID 29163765, 2017). "We propose that in the absence of brain-resident CD8+ T cells, unrestricted CD4+ T cell activity and IgE production could be responsible for disease aggravation in lupus-prone mice." (PMID 28098193, 2017). "Interestingly, PTEN expression is significantly decreased in SLE B cells; however, to the best of our knowledge, its expression in lupus CD4+ T cells (especially TFH) has not been investigated yet." (PMID 27635407, 2016). "Furthermore, global histone H3K9 hypomethylation, but not H3K4, in both active and inactive lupus CD4+ T cells has been suggested." (PMID 27669210, 2016). "In addition, there was a correlation of the frequency of CD4+DPP-IV high+ cells with the clinical severity in patients with multiple sclerosis, while reduced levels of the DPP-IV expression in BMNC were observed in highly active systemic lupus erythematosus." (PMID 26353808, 2015). "Recent studies showed that negative regulators of CD4+ T cells activity—miR-142-3p and miR-142-5p—are significantly downregulated in lymphocytes of lupus patients and that no treatment (corticosteroids, antimalarial or immunosuppressive agents) affects expression level of either miR-142-3p or -5p." (PMID 26473848, 2015).
lupus (continued). "However, both lpr and Nba2 mice deficient in BCMA unexpectedly develop an accelerated lupus-like disease that is associated with aberrant BAFF levels, germinal center formation, and CD4+ T cell-dependent autoantibody production, suggesting an important role for BCMA in the context of murine lupus." (PMID 25010693, 2014). "Furthermore, PTX3 is redundant for the production of lupus autoantibodies in these mice, albeit it fosters the clearance of apoptotic cells and (thereby) inhibits the expansion of CD4/CD8 double negative T cells." (PMID 21637713, 2011). "Interestingly, dysregulated TFH cell function has been reported in patients with lymphoma, such as angioimmunoblastic-T-cell lymphomas (AITL), and primary cutaneous CD4+ small/medium-sized pleomorphic T-cell lymphoma (CSTCL) and autoimmune diseases, such as systemic lupus erythematosus (SLE)." (PMID 21750724, 2011). "In conclusion, our results demonstrate that exogenous expansion and adoptive transfer of the regulatory T cell subset defined by CD4 and CD25 expression produces a population of highly suppressive, long-lived Tregs capable of delaying the onset of glomerulonephritis in a murine model of lupus." (PMID 19551149, 2009). "Finally, we show that exogenously expanded, adoptively transferred CD4+CD25+ T cells containing a mixed population of Foxp3+Tregsand co-expanded Foxp3−Teffs, to lupus prone B/W mice can enhance suppression of autoreactive lymphocytes and delay the development of autoimmune disease." (PMID 19551149, 2009). "Furthermore, contrary to previous reports demonstrating decreased proportions of CD4+CD25+ Treg cells in lupus, we did not observe any alterations in this population." (PMID 18783591, 2008). "In the context of systemic lupus erythematosus (SLE), the administration of corresponding metabolic inhibitors, as metformin for OXPHOS and 2-Deoxy-D-glucose (2-DG) for glycolysis, reduce cytokine production of CD4+ T cells and ameliorate kidney damage." (PMID 39737193, 2024). "Notably, these cells could inhibit CD4+CD25− T cell inflammatory responses by reducing TCR-zeta chain expression and inducing T cell apoptosis, whereas the regulatory function of these cells on T cells is impaired in lupus mice." (PMID 37500293, 2023). "Furthermore, Cheng and coworkers have reported in both lupus-prone MRL/lpr mice and lupus patients that resolvin D1, a pro-resolving DHA metabolite, ameliorates disease progression by increasing Treg differentiation and decreasing Th17 differentiation from naïve CD4+ T cells." (PMID 36875087, 2023). "Moreover, GrB-producing Breg cells in lupus mice failed to suppress T cell-mediated proinflammatory responses, partially due to the impaired capacity of downregulating the T cell receptor-zeta chain and inducing CD4+CD25− T cell apoptosis." (PMID 37500293, 2023). "We found that the frequency of CD4+CD8+ thymocytes was significantly decreased, while the ratios of CD4+/DP and CD8+/DP were significantly elevated in IL-39 plasmid-treated recipients, indicating that IL-39 could exacerbate thymic damage in both lupus-like and scleroderma-like cGVHD models." (PMID 35655245, 2022). "Interestingly, the traditional SLE drug, mycophenolic acid (MPA, an immunosuppressant), was able to reverse the abnormal histone global hypoacetylation status in lupus CD4+ T cells by upregulating HAT expression and downregulating HDAC expression." (PMID 35159315, 2022). "Interestingly, in systemic lupus erythematosus (SLE), blocking CD200R on CD4+ T cells reduced the Th17 percentage in vitro." (PMID 34769408, 2021). "Among aberrant T cells of MRL/lpr mice, double-negative (DN) T cells, defined by the absence of CD4 and CD8, are the major pathogenic immune cell subset and have the ability to produce proinflammatory cytokines like IFN-γ and IL-17 which has been linked to lupus pathogenesis both human and mice." (PMID 33986739, 2021).
lupus (continued). "SIRT1 overexpression was found in CD4+ T cells of a murine lupus model, suggesting that upregulated SIRT1 may contribute to the SLE pathogenesis." (PMID 33981300, 2021). "The aim of this study was to investigate BTLA expression on regulatory and effector CD4+ T-cells in SLE patients with and without lupus nephritis (LN) during active and inactive disease." (PMID 31514450, 2019). "Collectively, the absence of CD137L induces an immune deviation of CD4+ T cells by polarizing them towards the Th17 phenotype and reduces IL-10-producing CD11b+ cells and hence serum anti-inflammatory IL-10 levels, resulting in more severe lupus-related glomerulonephritis and dermatitis." (PMID 31500130, 2019). "Clonal expansion of CD4+CD28− T cells is also detected in a peripheral circulation in other immune mediated disorders, such as multiple sclerosis, inflammatory bowel disease, and systemic lupus erythematosus (SLE)." (PMID 29370129, 2018). "Notably, therapeutic administration of JES6/IL-2 complexes in a spontaneous model of lupus was shown to ameliorate ICGN, arguing in favor for our hypothesis that stimulation of donor CD4+ T cells by JES6/IL-2 complexes canceled out the beneficial effect of Treg stimulation." (PMID 29670626, 2018). "Thus, hCDR1 down regulated (in vivo and in vitro, in murine SLE models and in human lupus) pro-inflammatory cytokines, apoptotic factors, B-cell stimulatory factors (BAFF/BLyS) and up regulated immunosuppressive cytokines with the induction of CD4+CD25+FoxP3+regulatory T-cells." (PMID 23555966, 2013). "Dex drug and W treatment did not affect Tregs (CD4+ CD25+ FOXP3+) and Bregs (CD5+ CD1d+) in lupus mice." (PMID 40158179, 2025). "Additionally, TGP treatment significantly increased the proportion and number of Tregs among lupus CD4+ T cells, indicating that TGP may inhibit autoimmunity in SLE patients by promoting Treg differentiation." (PMID 41458964, 2025). "Real-time bioenergetic profiles also showed that IGU treated CD4+ T cells have lower glycolysis and glycolytic capacity, which implied IGU also played a key role in regulating the T cells in other diseases which are characterized by glycolysis, such as systemic lupus erythematosus (SLE)." (PMID 35720293, 2022). "Similarly, systemic lupus erythematosus (SLE) mice without ABCs display defects in T cells, with fewer activated/memory CD4+ T cells and less IFNγ+CD8+ T cells compared to mice with ABCs." (PMID 35298565, 2022). "The percentages of CD3+, CD3+/CD4+, CD3+/CD8+, CD4+/CD8+, CD3−/CD16+ CD56+, and CD3−CD19+ in the peripheral blood of patients (n = 80) classified into lupus nephritis, blood involvement, and joint involvement and SLE in different active stages were detected by flow cytometry." (PMID 36045722, 2022). "Since CD4+ T cells act as main helper cells for plasma cell production and cytokines secretion, we suggest that the decreased expression of DERL3 in lupus CD4+ T cells may contribute to the pathogenesis of SLE." (PMID 36046235, 2022). "In this regard, if CD4+ T cells are transferred to F1-hosts without donor CD8+ T cells, a lupus-like cGVHD develops instead of aGVHD." (PMID 35628145, 2022). "According to current studies, a critical functional link between miRNAs and the lupus CD4+ T cells have been connected by the potential interplay between miRNAs and critical molecules such as SLAM family, STAT-1, DNMT1 which contribute to T cells abnormalities and hypomethylation in SLE." (PMID 34408748, 2021). "While extensive evidence underpins the essentiality of CD4+ and CD4-CD8- double-negative T cells in lupus pathogenesis, roles for CD8+ T cells have also been increasingly recognized." (PMID 33763079, 2021). "We found that EGR2 inhibition significantly reduced IFNγ production in PMA and ionomycin activated MRL-lpr lupus CD4+ T cells, but not control MRL CD4+ T cells." (PMID 32646370, 2020).
lupus (continued). "Together, our data suggest that EGR2 positively regulates IFNγ production in MRL-lpr lupus CD4+ T cells, but not in control MRL CD4+ T cells." (PMID 32646370, 2020). "In this study, we uncovered a disease-stage dependent accumulation of TCRβ+CD138+ cells in various organs of lupus-prone MRL/Lpr mice, which are overwhelmingly positive for B220, but negative for CD4 and CD8 expression." (PMID 32849532, 2020). "NETs containing ISG15 from SLE patients induce IFNγ production from diverse cellular subsets: To address the functional impact of ISG15 on the NETs from lupus patients, the production of IFNγ in subsets of T lymphocytes (CD4+ and CD8+) and NK cells was evaluated by multiparametric flow cytometry." (PMID 33176801, 2020). "The proportion of CD4+ and CD8+ T cells did not change; however, an elevated level of IFNγ, which is known to promote lupus in both humans and MRL/lpr mice, was found in the serum of mice treated with vancomycin before disease onset." (PMID 33240280, 2020). "Unlike lupus murine models, homozygous Tyk2P mice were fully protected from EAE, and infiltrating CD4+ T cells within the CNS." (PMID 30740104, 2019). "While limited data has been shown in lupus CD8+ T cells in relation to vitamin D, the current data have demonstrated that CD8+ T cells express a higher VDR level than CD4+ T cells in the non-SLE setting." (PMID 30103428, 2018). "The expression of the SLAM family receptors on T-cell subpopulations [CD4, CD8 and double negative (DN) T cells] was measured and compared between lupus patients with active renal disease and those in remission." (PMID 28387859, 2017). "Freshly isolated SMCs from pristane-induced lupus mice were activated with ConA (2.5 μg/ml) with or without resveratrol and the levels of CD69 and CD71 were then measured, which are markers of CD4+ T lymphocyte activation." (PMID 25501752, 2014). "As a consequence CD4/CD8 double negative T cells accumulate and eventually undergo secondary necrosis which increases the exposure of potential lupus autoantigens to phagocytes and antigen-presenting cells." (PMID 21637713, 2011). "Nonetheless, these correlations between FOXP3 expressing T cells and memory T cells did not exist in lupus patients, while a positive correlation between CD25+ FOXP3- CD4+ T cells and memory T cells was maintained." (PMID 21708033, 2011). "Lack of PTX3 impaired the phagocytic uptake of apoptotic T cells into peritoneal macrophages and selectively expanded CD4/CD8 double negative T cells while other immune cell subsets and lupus autoantibody production remained unaffected." (PMID 21637713, 2011). "They found that lupus patients had CD4 T cell lymphopenia, a decrease in naïve CD4+ T cells, clonal expansion of cytotoxic GZMH+ T cells, and a limited presence of CD8+ T cells, yet not CD4+ T cells." (PMID 40948783, 2025). "Besides, we found that neddylation inactivation notably suppressed the proliferation of CD4+ T cells and blocked the differentiation of T follicular helper (Tfh) cells in MRL/lpr mice and pristane-induced lupus models (data not shown)." (PMID 38221551, 2024). "Thus, rapamycin increased ATP production in CD8+ but not CD4+ T cells of B6.TC/Rab4AQ72L mice, indicating that rapamycin selectively enhanced the mitochondrial metabolic fitness of CD8+ T cells of lupus-prone B6.TC/Rab4AQ72L mice." (PMID 38519468, 2024). "For example, systemic lupus erythematosus (SLE) CD4+ T cells of lupus-prone mice had enriched OXPHOS and glycolytic pathways and combined treatment with 2-DG and metformin in vivo could normalize metabolism of these CD4+ T cells and reverse biomarkers of the disease." (PMID 34385998, 2021). "The excessive proliferation of CD4+, CD8+, and double-negative (CD4–CD8–) T lymphocytes was observed in murine models of lupus and SLE patients, while increased proliferation rate of naive and functionally differentiated CD4+ T cells was detected in SSc patients." (PMID 35095547, 2021).
lupus (continued). "Importantly, we have shown that EGR2 is critical for Th1 differentiation and that inhibition of EGR2 in vitro suppresses IFNγ production only in MRL-lpr lupus CD4+ T cells, but not control MRL CD4+ T cells." (PMID 32646370, 2020). "We performed an intracellular flow cytometry assay to quantify EGR2 expressing cells and EGR2 protein expression intensity (determined by Median Fluorescence Intensity, MFI) in gated splenic CD4+ T cells of MRL-lpr and B6.sle123 lupus mice and non-autoimmune controls (MRL and B6)." (PMID 32646370, 2020). "Intriguingly, a high salt diet seems to accelerate the progression of lupus in MRL/lpr mice but not MRL/mpj and Balb/c mice, and, finally, NaCl seems to induce DNA hypomethylation of CD4+T cells and to enhance the expression of the hydroxyltransferases TET2 and TET3." (PMID 31060286, 2019). "Recently, a subgroup of CD4+FoxP3+ T cells negative for CD25 has been detected in multiple immune regulatory diseases, such as systemic lupus erythematosus (SLE), HIV and Mycobacterium tuberculosis infection, and non-Hodgkin lymphoma (NHL)." (PMID 36064312, 2022). "In addition, antimiR-21 treatment altered CD4+/CD8+ T cell ratios towards those of the non-autoimmune control mice and reduced Fas receptor-expressing B cells, suggesting that miR-21 plays a critical role in regulating autoimmune responses in lupus." (PMID 22230293, 2012). "It has also been described for HERV-E.FABP7 in leukemic B cells; HERV-E.PTN, HERV-E.EDNRB, and HERV-E.MID1 in placenta but not in blood cells; and HERV-E clone 4-1 in peripheral blood lymphocytes (CD4+, CD8+ and B cells) but not in neutrophils from patients with systemic lupus erythematosus (SLE)." (PMID 25785516, 2015).